BCL2 (BCL2 apoptosis regulator)
Diseases named in the same sentence as BCL2 in open-access papers (continued):
Sharing a sentence is not in itself a finding about the gene and the disease.
cancer (continued). "The aim of this study is to explore the protein–protein interaction (PPI) of BCL2 focusing on cancer-related proteins and their potential as a therapeutic target." (PMID 40136517, 2025). "We have previously demonstrated that FOXM1 knockdown (KD) induces sensitivity to cytotoxic or BCL2-targeted therapy in several human cancers, including AML." (PMID 39880086, 2025). "Combining Bcl-2 inhibitors with proteasome inhibitors offers a synergistic strategy to destabilize cancer cell survival by restoring apoptotic signaling." (PMID 40841912, 2025). "Preclinical results utilising cancer cell lines and mouse models have demonstrated that sonrotoclax is effective against both wild‐type Bcl‐2 and Bcl‐2 G101V, suggesting its potential to overcome venetoclax resistance associated with this mutation." (PMID 40619749, 2025). "The Bax/Bcl2 ratio increase can lead to mitochondrial‐mediated apoptosis by many anti‐cancer agents." (PMID 39542458, 2025). "Anti-apoptotic B-cell lymphoma-2 (BCL-2) family proteins are frequently overexpressed in various cancers, playing a pivotal role in cancer initiation and progression, as well as intrinsic or acquired resistance to therapy." (PMID 40699886, 2025). "Approaches targeting the modulation of Bcl-2 and Bcl-XL expression and activity have been shown to hold considerable potential in overcoming resistance by sensitizing cancer cells to Tx-induced apoptosis." (PMID 41114937, 2025). "This compound is known to induce cell apoptosis through an intrinsic pathway involving Bax, Bcl-2 and caspase-3 proteins, and it promotes cell cycle arrest by regulating mediators such as cyclin A, cyclin B1 and cyclin D1 in various cancer cells." (PMID 40005281, 2025). "The ranked the order of Bax/Bcl‐2 expression from highest to lowest and the outcome was fibroblasts > neuron‐glial cultures > BT‐474 cancer cells." (PMID 39760157, 2025). "BCL2 is an important apoptosis regulator, deregulated in many cancers, and is currently a promising drug target in clinical trials." (PMID 40133476, 2025). "Cancer cells often exhibit elevated expression of Bcl-2 or Mcl-1, which stabilize the mitochondrial membrane and inhibit cytochrome C release, thereby blocking caspase-9 activation and the subsequent apoptotic cascade." (PMID 41375095, 2025). "The complex regulation of apoptosis by Bax, along with its intricate interplay with anti-apoptotic proteins such as Bcl-xL and Bcl-2, plays a key role in influencing cancer cell survival and resistance to treatment." (PMID 40841912, 2025). "Recently, BH3 mimetic drugs that inhibit individual prosurvival family members have been developed to promote the apoptosis of cancer cells, and the BCL-2 inhibitor venetoclax is being used in combination therapy to treat AML." (PMID 41140443, 2025). "In the constructed pan-cancer drug–gene network, the top hub gene of the network was mTOR, which interacted with 45 drugs, followed by BCL2, STAT3, and EGFR." (PMID 40293950, 2025). "Upon treatment with MetR, various cancer cell lines demonstrate increased expression levels of Bcl-2 family members, including Bax and Bid, along with decreased expression level of Bcl-2." (PMID 40565337, 2025).
cancer (continued). "For cancer cells to survive their hostile environment, the anti-apoptotic BCL2 proteins must manage to keep the BH3-only proteins in check to prevent BAX/BAK pore formation and MOMP." (PMID 40113751, 2025). "One such compound, NuBCP-9, a highly promising anticancer peptide, specifically induces apoptosis in cancer cells by exposing the BH3 domain of Bcl-2, thereby inhibiting the survival function of Bcl-XL." (PMID 41114937, 2025). "Continued preclinical and clinical studies are essential to validate the efficacy and safety of Bcl-2 inhibitors in various cancer types." (PMID 40841912, 2025). "In our study, we evaluated a range of pro-apoptotic molecules in the context of HIV infection, focusing on BCL-2/BCL-xL antagonists developed as cancer therapeutics and advanced to clinical trials." (PMID 40141414, 2025). "For instance, curcumin can strengthen gemcitabine’s impact by lowering the levels of proteins that help cancer cells avoid death (like Bcl-2) and reducing NF-κB activity." (PMID 40427617, 2025). "Activation of BCL-2 expression in various cancers suggested the essential role of BCL-2 in apoptosis pathways (Lindsay, Esposti & Gilmore, 2011)." (PMID 41180483, 2025). "The new series exhibited a selective sub-micromolar IC50 growth inhibitory effect against Bcl-Bcl-2-expressing human cancer cell lines." (PMID 40725000, 2025). "This study illustrates a detailed investigation into the protein–protein interactions (PPIs) of BCL2 and its potential role in cancer progression and therapeutic resistance." (PMID 40136517, 2025). "Secondly, cancer cells frequently develop resistance to Bcl-2 inhibitors, necessitating the identification of resistance mechanisms and the development of strategies to overcome them." (PMID 40841912, 2025). "More recent studies highlight Bcl-2’s involvement in promoting GC metastasis by enhancing cancer stemness and resistance to targeted therapies." (PMID 40841912, 2025). "BAX (pro‐apoptotic) and BCL2 (anti‐apoptotic), members of the mitochondrial apoptotic pathway, are regulated during carcinogenesis and prevent the death of cancer cells." (PMID 40576246, 2025). "For instance, by targeting the Bcl-2/Bax interaction, these peptides can effectively promote apoptosis and overcome resistance mechanisms in cancer cells." (PMID 41114937, 2025). "The inhibition of specific Bcl-2 proteins has been described as a promising therapeutic strategy for cancer." (PMID 39857806, 2025). "ST1326 sensitizes cancer cells to Bcl-2 inhibition, upregulates caspase-9, −8, and −3 mRNA and protein levels, and induces apoptosis; these effects have also been confirmed in canine cancer cell models." (PMID 41219902, 2025). "Dysregulation of apoptotic pathways allows cancer cells to evade cell death, for example, through overexpression of anti-apoptotic proteins like Bcl-2 or downregulation of pro-apoptotic factors, thereby diminishing PTX-induced cytotoxicity." (PMID 41462867, 2025). "The development and clinical trials of BCL-2 inhibitors such as Venetoclax have demonstrated efficacy in reducing cancer cell survival by restoring apoptosis." (PMID 39940838, 2025). "It has been demonstrated that ALA induces apoptosis through the mitochondrial apoptotic pathway by significantly inhibiting Bcl-2 expression and increasing Bax expression in various cancer cell lines such as OSA, HepG2, and MCF-7." (PMID 40019527, 2025). "In our research, we used RT-quantitative real-time PCR to analyzewhether the expression ratio of Bax to Bcl-2 mRNA correlates withapoptosis or the proliferative activity of cancer cells." (PMID 40631712, 2025). "Mechanistically, SF3A3 promotes the alternative splicing of c‐FOS, a proto‐oncogene implicated in cancer progression, leading to increased full‐length c‐FOS expression and upregulation of the anti‐apoptotic Bcl2/Bax ratio." (PMID 40598817, 2025).
cancer (continued). "Gene expression analysis revealed significant modulation of key genes involved in cancer progression, including upregulation of IL-6, and downregulation of anti-apoptotic genes such as BCL2, HIF, and Survivin." (PMID 41310357, 2025). "Specifically, Bcl-2 can foster cancer stemness by preventing apoptosis in the cancer stem cell population, allowing these highly tumorigenic and drug-resistant cells to survive and proliferate." (PMID 40841912, 2025). "AS1411 itself induces cancer cell death by inhibiting DNA replication and suppressing BCL-2 mRNA stabilization, thereby halting cell proliferation." (PMID 40277546, 2025). "Mechanistically, β-sitosterol can induce cancer cell apoptosis by modulating key regulators: it elevates the Bax/Bcl-2 ratio and activates caspases via the intrinsic mitochondrial pathway." (PMID 40808836, 2025). "Accumulating evidence from numerous studies has demonstrated that miR-205 can directly modulate BCL-2 expression, thereby regulating apoptotic processes in multiple cancer types." (PMID 41001034, 2025). "EECS was shown to induce apoptosis in K562 cells and suppress cancer progression by upregulating Bax and Caspase‐3 and downregulating Bcl‐2." (PMID 41231037, 2025). "The B-cell lymphoma-2 (Bcl-2) family proteins, key regulators of apoptosis, are frequently dysregulated in cancer, tipping the balance of cell survival and apoptosis in favor of survival." (PMID 40841912, 2025). "The findings showed that combined therapy induced apoptosis in cancer cells by reducing cyclin D1 and Bcl‐2 expression while improving Bax and caspase‐3 expression." (PMID 40964147, 2025). "The Bcl-2 siRNA (siBcl-2) can down-regulate the antiapoptotic protein Bcl-2 expression in cancer cells, which is responsible for inhibiting cancer cell growth." (PMID 40497830, 2025). "New findings argue that the inhibition of BCL-2 proteins is a good alternative in the field of targeted cancer therapy." (PMID 40650808, 2025). "It has been shown to inhibit cancer growth through various mechanisms, including apoptosis induction via caspase activation and Bcl2 inhibition, PI3K/AKT/mTOR and MAPK/ERK pathway modulation in addition to angiogenesis inhibition via VEGF and MMP9 inhibition." (PMID 40396612, 2025). "NF-κB also modulates the expression of multiple anti-apoptotic genes, namely BIRC5 (Survivin), c-FLIP, B-cell lymphoma-extra large (BCL-XL), and B-cell lymphoma-2 (BCL-2), enabling cancer cell survival )." (PMID 40420174, 2025). "Due to its critical role in cancer progression, Bcl-2 is a well-established target for cancer therapy." (PMID 40076649, 2025). "Previous experiments revealed that IFN-γ-overexpressing BMSCs upregulated pro-apoptotic BAX expression, downregulated anti-apoptotic BCL2, and promoted apoptosis in cancer cells." (PMID 40642092, 2025). "Cancer cells prevent apoptosis through modulation of Bcl-2 proteins, via upregulation of anti-apoptotic and pro-survival proteins, such as BCL-2, BCL-XL, and MCL1, or/and downregulation of pro-apoptotic proteins, such as BAX, BAK, and BOK." (PMID 39860065, 2025). "The extract was able to induce apoptosis of cancer as revealed by Bcl-2, Bcl-xL, and caspase-3 (p<0.05 and p<0.001) signaling pathways." (PMID 38629020, 2024). "ABT‐263 is an orally available BAD‐like BH3 mimetic with a BCL‐2 inhibitor and is currently under clinical investigation to treat multiple cancers." (PMID 38037859, 2024). "Similar to siRNA, ASO target genes are involved in cancer differentiation, growth, proliferation, and survival, such as Bcl-2, survivin, EGFR, signal transducer and activator of transcription 3 (STAT3), and PD-L1." (PMID 39407665, 2024).
cancer (continued). "This establishes an important role for Itch in regulation of extrinsic and intrinsic apoptosis, mitochondrial cholesterol levels and provides insight to mechanisms that contribute to TRAIL, Bcl-2 inhibitor and cisplatin resistance in cancer cells." (PMID 38216558, 2024). "The effects of YAP silencing in Bcl-2 overexpressing cancer cells were evaluated in migration and cell viability assays in relation to different stiffness conditions." (PMID 38755629, 2024). "BCL2 inhibitors (Venetoclax, Navitoclax) are already used in clinically in other cancers and their side effect profiles are well understood, justifying them for planning future clinical trials in combination therapy." (PMID 38451783, 2024). "Abnormal STAT5 signaling in different types of cancers increases the expression levels of cyclin D, Bcl-2, and MMPs, among others, which ultimately leads to enhanced cell proliferation, survival, and metastasis." (PMID 38806527, 2024). "While apoptosis was enhanced by garlic SEVs on cancer cells, there was an increase in some antiapoptotic Bcl-2 expression levels and a reduction in Cas3 activity on a healthy HUVEC cell line." (PMID 39050709, 2024). "Several studies have reported similar findings, demonstrating that natural extracts or compounds can modulate Bcl2 expression, resulting in apoptotic cell death in cancer cells." (PMID 38738026, 2024). "Beyond TNBC, this research paves the way for exploring BCL2-targeted therapies in other cancers with BCL2 overexpression." (PMID 38928195, 2024). "Overall, the findings of this study hold several biological significances, for instance having information on SNPs in the Bcl-2 gene would help identify potential biomarkers for cancer diagnosis and treatment." (PMID 39840282, 2024). "There is also a correlation between the extent of Bcl-2 expression and responsiveness of cancer cells to BFC1108." (PMID 38329389, 2024). "The qPCR results of our study reveal significant increases in the mRNA levels of the apoptotic marker CSP3 and BCL2 expressions in both premalignant and cancer cells." (PMID 39062071, 2024). "Conventional wisdom suggests that the primary anti-cancer effect of BCL-2 inhibition is through induction of cancer cell death." (PMID 38549077, 2024). "In the present study, Bcl2 expression was significantly increased in cancer tissues and Bax was significantly decreased in cancer tissues compared with non-cancerous tissue." (PMID 38072891, 2024). "Some chemotherapeutic agents increase the sensitivity of drug-resistant cancer cells through reducing intracellular levels of Bcl-2, resulting in resistant cell apoptosis." (PMID 38542707, 2024). "It is involved in the release of apoptotic factors and interacts with anti-apoptotic proteins such as Bcl-2, Bcl-xL, and HK, which are often overexpressed in cancer cells." (PMID 39456237, 2024). "Bcl-2 is estimated to be overexpressed in several human cancers, such as leukemia, colorectal carcinoma, breast cancer, and prostate cancer, among others." (PMID 39517292, 2024). "Consequently, EZH2 inhibitor-resistant ARID1A-mutated cells become highly sensitive to BCL2 inhibitors like ABT263 suggesting that BCL2 inhibition alone or in combination with EZH2 inhibition represents an improved therapeutic strategy for ARID1A-mutated cancers." (PMID 39471843, 2024). "Numerous curcumin analogues have been reported to promote apoptosis in cancer cells by inducing caspase-3 cleavage/activity and Bcl-2 protein suppression." (PMID 38542474, 2024). "Bcl-2 is an oncoprotein found in cancer proteins in the nuclear membrane, some mitochondria, and the outer membrane that can protect cells from apoptosis." (PMID 39199151, 2024). "Disarib demonstrates a promising multifaceted approach for treating TNBC by targeting BCL2 and disrupting cancer cell survival, metabolism, and migration." (PMID 38928195, 2024).
cancer (continued). "Helenalin has been evidenced to trigger cell death apoptosis-resistant Bcl-2 overexpressing cancer cells such as leukemic Jurkat, breast MCF-7, and pancreatic L6.3pl cell lines." (PMID 38529189, 2024). "Bax is a regulator of Bcl-2 activity, both Bcl-2 and Bax play an important role in cell apoptosis, and Bcl-2 is increased in most cancers, while Bax is decreased." (PMID 38510491, 2024). "Venetoclax has demonstrated significant efficacy in inducing apoptosis in Bcl‐2‐dependent cancer cells, with a favorable safety profile compared with earlier, less specific Bcl‐2 inhibitors." (PMID 39239068, 2024). "Apoptosis-regulating proteins from the B-cell lymphoma-2 (BCL-2) family are of continued interest as they represent promising targets for anti-cancer therapies." (PMID 39695189, 2024). "Numerous research data described significant regulatory effects of phytochemicals in Bax/Bcl-2/caspase-3 signaling on cancer." (PMID 38464730, 2024). "BCL2 and its family proteins function as inhibitors and activators of the intrinsic apoptotic pathway to govern the fate of cancer cells." (PMID 38918775, 2024). "The interaction between MMP-9 and BCL-2 can promote cell survival and contribute to cancer progression." (PMID 38575697, 2024). "Changes in down-regulated genes were ETV4 (ETS Variant Transcription Factor 4) and ETV5 (ETS Variant Transcription Factor 5) are related to transcriptional regulation, EML4 (EMAP like 4), BCL2 and Myc are related to cancer development." (PMID 39834948, 2024). "On the other hand, vinorelbine is an anti-microtubule agent that triggers apoptosis in cancer cells by reducing the formation of heterodimers between Bcl2 and the pro-apoptotic gene BAX." (PMID 37622179, 2024). "Since it has been indicated that an increased ratio of pro-apoptotic BAX protein to anti-apoptotic Bcl-2 protein expression can be associated with apoptosis, it’s reported that 2-ME increases BAX/Bcl-2 ratio in some cancer cells." (PMID 39167288, 2024). "In cancer cells, BCL-2 is usually upregulated, inhibiting the proapoptotic BAX; therefore, inhibiting apoptosis." (PMID 38246945, 2024). "Anti-cancer drugs exert their effects by downregulating anti-apoptotic proteins such as Bcl-2, cIAP, and survivin, thereby promoting apoptosis." (PMID 39273231, 2024). "The critical mediators of intrinsic and extrinsic apoptotic signaling pathways, such as Bak1, Casp7, Bid, Bcl2, was significantly downregulated in cancer cells exposed to 5-FU." (PMID 38609535, 2024). "Mutants altering the BCL2 TMD hetero-interactions with pro-apoptotic BAX remain particularly interesting due to the possible impacts on cancer cell survival and therapeutic resistance." (PMID 38670940, 2024). "Resistance to apoptosis is a hallmark for cancer and overexpression of anti-apoptotic proteins like BCL-xL/BCL-2 are partly responsible for it18,56,57." (PMID 38548768, 2024). "This study aimed at addressing the previous screening limitations and improving the likelihood of discovering novel, effective BCL2 inhibitors, marking a significant step forward in cancer therapy research." (PMID 38785951, 2024). "By promoting Cyclin D1 and Bcl-2 expression, the NF-κB pathway drives cell cycle progression and promotes the proliferation of cancer cells." (PMID 39169391, 2024). "Acute oral toxicity was determined, and a molecular docking study was performed using target proteins associated with cancer, including, HMG-CoA, Bcl-2, Mcl-1, and VEGFR-2." (PMID 39769118, 2024).